INS (insulin)
Diseases named in the same sentence as INS in open-access papers (continued):
Sharing a sentence is not in itself a finding about the gene and the disease.
cancer (continued). "Inhibition of apoptosis, angiogenesis, and promotion of cancer cell proliferation and migration may involve high levels of leptin, while low levels of adiponectin may interrupt the AMP-activated protein kinase (AMPK) and the insulin-signal pathways, which lead to cancer cell proliferation." (PMID 36555323, 2022). "Additionally, there is an indirect mechanism reported that might be of considerable importance in subjects with high insulin levels and cancers with high levels of insulin and hybrid insulin/IGF-1 receptors." (PMID 33440701, 2021). "Interestingly, during the subclinical phase, insulin requirements might be affected by the undetected cancer leading to changes in treatment, thus appear to be favouring cancer for an unwary observer." (PMID 34535145, 2021). "However, our co-expression analysis suggests that PER3 could be involved in several molecular mechanisms related to cancer which include energy metabolism, signaling through cancer related pathways such insulin and PI3K/AKT signaling and cell cycle control." (PMID 34508103, 2021). "In the skin or body, they may synergise or drive de novo therapeutic outcomes that range from anti-inflammatory effects through to insulin sensitisation, dermal rejuvenation, keratinocyte migration, upregulation of hair follicle bulb stem cells or complementation of anti-cancer therapies." (PMID 34744723, 2021). "These combined effects might have a beneficial impact on biological mechanisms that interact directly or indirectly with cancer, such as improved insulin sensitivity and reduced chronic low-level inflammation, which is also linked with favorable immunomodulation." (PMID 33924417, 2021). "Therefore, it seems reasonable to hypothesize that diet could have profound effects on reducing cancer risk, especially if that diet is known to decrease body weight, lower insulin levels, and target the metabolic weaknesses of cancer cells." (PMID 34068325, 2021). "The involvement of the IGF-1R pathway and the potential role of miRNAs in cancer therapy prompted us to seek out dysregulating miRNAs that could be involved in the insulin/IGF-1R signaling pathway, as these miRNAs may represent potential PDAC therapeutic targets." (PMID 34440625, 2021). "Importantly, cancer cells frequently overexpress insulin and IGF-1 receptors." (PMID 33673109, 2021). "However, it also indicated a much more significant dose-dependent increase in the risk of cancer regardless of the type of insulin used." (PMID 33562380, 2021). "Insulin resistance (IR), defined by decreased responsiveness to insulin and characterized by reduced glucose disposal in nonhepatic tissues, is one of the obesity-related disorders posing a major risk toward cancer development and is associated with poor prognosis." (PMID 33671547, 2021). "Interestingly, many epidemiological studies suggest a reduced incidence of cancer in patients treated with metformin compared to other antidiabetic therapies, and this may be related to metformin-mediated reductions in endogenous insulin secretion." (PMID 34360563, 2021). "Therefore, reduction in insulin level prevents cancer cells from proliferating." (PMID 33198356, 2020). "However, preoperative long-term insulin therapy may lead to a delay in surgery, which may be a problem for some types of surgery, especially cancer surgery." (PMID 32993618, 2020). "Therefore, metformin treatment-related decrease in circulating insulin levels correlates to the ‘indirect’ anti-cancer/anti-tumor effects of metformin via the inhibition of the mitogenic and pro-angiogenic signaling mechanisms which are otherwise activated by insulin and IGF1." (PMID 32883003, 2020). "Interestingly, the results of pathways enrichment analysis can be divided into two function modules, including cell cycle regulation (such as MAPK, PI3K-Akt, and VEGF signaling pathways) and metabolic pathway (such as insulin signaling pathway, and central carbon metabolism in cancer)." (PMID 31998398, 2020).
cancer (continued). "Insulin and IGF2 can bind the IRA, while IRB only binds insulin with high affinity, whereby different downstream pathways are activated: IRB fulfills an important role in glucose homeostasis, whereas IRA, the embryological splice variant, is the dominantly expressed isoform in many cancer cells." (PMID 33260481, 2020). "Moreover, the decrease in insulin level that accompanies the indicated ketonemic conditions correlates with a decrease in insulin-like growth factors, which promotes the proliferation of cancer cells." (PMID 32192146, 2020). "It has been further hypothesized that inhibition of DDR1 may be a way to downregulate the tumor-inducing actions of the insulin/IGF system in human cancer cells while simultaneously inducing differentiation of cells without affecting the IR-B mediated metabolic actions." (PMID 32252327, 2020). "However, long-term insulin therapy may lead to a delay in surgery, which may be a problem, especially in cancer surgery." (PMID 32993618, 2020). "Therefore, at the start of treatment with insulin and insulin analogs, high number of IR-A are phosphorylated and activated, which may play an important role in the process of cancer development and progression." (PMID 31555212, 2019). "Hence, insulin affecting cancer cell metabolism by downregulating the GRB2 may have key meaning for the planning of novel treatments." (PMID 31719636, 2019). "Moreover, the sensory threshold of the insulin-controlled glucose uptake in the muscle/fat cells is significantly elevated during multi-step cancer progression, for example, in transition from hyperplasic lesions to islet tumors, but together with an increased risk of circulating glucose deficit." (PMID 31019893, 2019). "Moreover, obese people have downregulated expression of adiponectin, an adipokine with anti-inflammatory and insulin-sensitizing properties, which can play an etiologic role in mutagenesis and may contribute to the development of cancer." (PMID 31681585, 2019). "However, over the same period the explosion of information from cancer genetics has changed our understanding of cancer etiology and this review aims to revisit the potential role of metabolic regulation and insulin/IGFs in the common epithelial cancers in the light of this new understanding." (PMID 30809194, 2019). "Thus, researchers speculate that similar insulin analogs that show high affinity for IGF-1R in vitro may have pro-proliferative and cancer-causing effects." (PMID 31555212, 2019). "Methylglyoxal affects several cellular functions such as insulin signalling, mitochondrial respiration and glycolysis, whilst high-dose methylglyoxal therapy has been highlighted as a potential therapeutic option in cancer settings due to its cytotoxic effects." (PMID 31654171, 2019). "Insulin has effects on cell proliferation, and may promote cancer through this mechanism." (PMID 30862906, 2019). "Inflammation, insulin and the insulin like-growth factor axis, sex steroids, and specific dietary components or nutrients have all been hypothesized to play critical roles in the link between diet, body weight, physical activity and cancer development." (PMID 30390014, 2018). "There is a link between obesity and numerous cancer incidences, but in terms of survival, studies have proposed that increasing levels of insulin and insulin-like growth factors as well as increasing insulin resistance in obesity may negatively influence colorectal cancer survival." (PMID 30566456, 2018).
cancer (continued). "In this review, we summarize the role of Insulin/IGF signaling pathway in the reciprocal interactions of stromal cells with cancer cells in the PDAC microeinvironment and suggest a research line to that may create opportunities to develop novel treatments for PDAC." (PMID 29475434, 2018). "Therefore, it is possible that in this tumor, IR-A/Met hybrids, amplifying the biological response to HGF and insulin/IGFs, may contribute to cancer progression, chemotaxis, and haptotaxis." (PMID 30513575, 2018). "However, the underlining mechanisms of inhibition of fatty acid accumulation leading to prevention of cancer development in the obese associated with the insulin resistant model have not been clearly established." (PMID 29546056, 2018). "On the other hand, longevity is associated with genetic variation in insulin-FOXO pathways and the signalling pathway connecting insulin and FoxO transcription factors provides the most compelling example for a conserved genetic pathway at the interface between ageing and cancer." (PMID 28861129, 2017). "However, the different results obtained with the two glitazones (RGZ and PIO) suggested that, apart from restoring insulin-sensitivity, the two drugs might have differential mechanisms on cancer and thyroid cells." (PMID 29184536, 2017). "Unfortunately, we could not define treatment duration and consequently disentangle the insulin effect on cancer initiation and possible masked worse metabolic conditions (indication bias) or possible close monitoring practice (detection bias), as some authors did." (PMID 29070034, 2017). "However, the magnitude of these systemic effects may not be sufficient to impact cancer cell growth directly, especially in patients with normal baseline glucose and insulin levels or in cancers that are insensitive to insulin." (PMID 27775072, 2017). "In addition, insulin and IGF-1 have been implicated to play a role in cancer." (PMID 28768896, 2017). "Therefore, there is no clear recommendation regarding the use of insulin or insulin analog in relation to cancer risk." (PMID 29184536, 2017). "Other analyses yielded a lower risk for any cancer in men for 0.5–1, 2–3 and >6 years of insulin detemir use relative to that of human insulin, and an increased risk in men and women combined (RR 1.18, 95% CI 1.05, 1.33) for <0.5 years of insulin glargine use relative to that of insulin detemir." (PMID 28573394, 2017). "Low-volume high-intensity interval training has been shown to elicit positive changes in the sedentary population by improving VO2 peak and insulin sensitivity, and it is plausible that it could be an alternative and time efficient training mode for sedentary cancer survivors." (PMID 27781180, 2016). "Although it still remains a question as to whether, or to what extent, exogenous insulin therapy causes cancer progression in patients, no one can overlook the potential threat of insulin which has been confirmed by in vivo animal studies." (PMID 26939025, 2016). "However, a similar effect has been observed previously suggesting that pre-existing malignant cells may rapidly proliferate into fulminant cancer when stimulated by the growth hormone action of insulin." (PMID 27031113, 2016). "We reviewed human data to obtain the following preliminary conclusions concerning insulin/IGF-1 modulation in humans: (i) DR could be considered as a supportive treatment during cancer therapy due to its probable antitumor effects, and due to its beneficial effects on human metabolism." (PMID 26878387, 2016). "Also Outcome Reduction with an Initial Glargine Intervention (ORIGIN) trial did not demonstrated raised cancer risk among insulin users." (PMID 27724912, 2016). "Future investigation is required to clarify whether insulin use may only be associated with some types of cancer but not with others." (PMID 27906989, 2016). "Moreover, there is concern that insulin analogs may increase cancer because of a biased effect on IR signaling pathways." (PMID 25798130, 2015).
cancer (continued). "Therefore, insulin and IGFs may induce a cancer cell-specific signaling pathway aberrant from that of normal cells." (PMID 25866823, 2015). "In addition, the interaction among insulin, insulin-like growth factors (IGFs), and ovarian steroid hormones, such as estrogen and progesterone, could act synergistically during cancer development." (PMID 25866823, 2015). "However, the internal signals of a cancer cell are very different from those of normal cells because of the changes in genetic and/or epigenetic factors, thereby stimulating another signaling pathway in response to insulin and IGF." (PMID 25866823, 2015). "In addition to development, coordinated changes in splicing have been observed during myogeneic differentiation, differentiation of human erythrocyte, during epithelial mesenchymal transition, during chemically induced cell death, during cancer metastasis and after insulin stimulation." (PMID 26029240, 2015). "A recent nested case–control study suggested that insulin glargine may increase the risk of all cancer, while human insulin and other types of insulin analogs do not increase cancer risk." (PMID 26537234, 2015). "release of long-range cytokines (IL6, TNFa) that may promote insulin resistance in the liver and other metabolism-controlling organs, thus generating increased levels of circulating insulin that may in turn promote cancer growth." (PMID 26284118, 2015). "In addition to these pharmaceutical strategies, dietary modulation may also be useful in controlling the high serum IGF-I and insulin levels present in obese cancer patients." (PMID 26029167, 2015). "Therefore insulin glargine may have different effects on cancer development compared to other forms of insulin." (PMID 26537234, 2015). "Therefore, insulin and IGFs may lead to various effects depending on the combination of half receptors in cancer cells." (PMID 25866823, 2015). "More recently, data from French national health insurance databases indicate that in a large cohort of more than 70,000 patients newly treated by long-acting insulin, there was no increased risk of cancer observed in insulin glargine users compared with other long-acting insulin users." (PMID 25329887, 2014). "Thus, the ability of SRA to induce IR protein expression and increase downstream phosphorylations of IRS-1 and Akt in response to insulin may occur in these and possibly other cancers." (PMID 24743795, 2014). "Insulin is a peptide hormone and its receptor (InsR), a tyrosine kinase, can occur in two alternatively spliced isoforms: InsR-A and InsR-B; the former is the predominant isoform in fetal life and is also the main subtype expressed in cancer as an ‘oncofetal’ phenomenon." (PMID 24493753, 2014). "Although the secondary insulin-lowering action of metformin may contribute in specific cases, interest in biguanides as potential anti-neoplastic agents relates to evidence that they induce energetic stress in cancer cells." (PMID 25017630, 2014). "Finally, relative overexpression of IR isoform A (IR-A) in (pre) cancer tissues may play a key role in the development and progression of human cancers during treatment with insulin (analogs)." (PMID 24904529, 2014). "More recently, two large cohort studies from the French health insurance information system and the Inovalon Medical Outcomes Research for Effectiveness and Economics Registry showed no increased risk of any cancer in insulin glargine users compared with other long-acting insulin users." (PMID 25329887, 2014). "There is a possibility that diagnosis of cancer during the first year of follow-up may not be associated with insulin treatment." (PMID 25329887, 2014). "A recent nested case-control study suggested that insulin glargine may increase the risk of all cancers, while human insulin and other types of insulin analogs do not increase cancer risk." (PMID 24466131, 2014).
cancer (continued). "Indeed, we uncovered some interesting differences, which may hold clues to the role of insulin and insulin signalling at different cancer stages." (PMID 25373319, 2014). "It seems that many tumours, at least initially, still respond to the communal metabolic signals (particularly the main activators of the PI3K-pathway, insulin and IGFs) and these signals may constitute part of the context that enables the cancer to progress: indicative that the ‘soil’ is fertile." (PMID 23907184, 2013). "Most recent meta-analysis of seventeen observational studies demonstrated that metformin was associated with 39% lower cancer risk (summary RR 0.61; 95% CI; 0.54–0.70) as comparing to reference therapies (insulin, sulfonylureas, or no medication) taken together." (PMID 23476808, 2013). "This role of insulin may be more significant in cancer cell biology than recognised previously." (PMID 23983688, 2013). "Although these findings suggest an insulin-independent, direct anti-tumoral activity for metformin, it remains unknown whether cancer cell-autonomous alterations that are known to drive insulin/IGF-1-independent, DR-resistant tumors preclude the anti-cancer activity of metformin." (PMID 23986086, 2013). "These earlier analyses are complicated by a variety of therapeutic interventions (insulin, metformin, oral hypoglycemics, angiotensin receptor antagonists, statins, etc.)commonly employed in diabetic therapy that also may influence the incidence of cancer." (PMID 23405181, 2013). "Moreover, insulin users showed higher risks of overall and cancer mortality." (PMID 23308218, 2013). "Whether insulin secretion modifies cancer development or simply the mortality risk (prognosis) is not clear from the current analyses." (PMID 23405181, 2013). "Recent epidemiological studies suggest that treatment with insulin may promote cancer growth." (PMID 24175949, 2013). "However, beneficial effects of insulin outweigh potential cancer risks." (PMID 23209929, 2012). "Chronic hyperinsulinemia, in affected individuals, may promote cancer, as insulin can exert its oncogenic potential via abnormal stimulation of multiple cellular signaling cascades, enhancing growth factor-dependent cell proliferation and/or by directly affecting cell metabolism." (PMID 22701472, 2012). "However, experiments using other cell lines and, in particular, human skeletal muscle cells, coronary artery cells, blood vessel endothelium cells, normal epithelial breast, and cancer cell lines have suggested a mitogenic and metabolic potency of insulin glargine similar to that of human insulin." (PMID 22685467, 2012). "The biological processes linking high BMI to cancer risk have not yet been clearly identified, but the potential mechanisms include insulin and insulin-like growth factor I, sex steroids, or adipokines acting on the thyroid to stimulate cell proliferation and suppress apoptosis." (PMID 22276106, 2012). "Our in vitro results support these findings and help to explain how insulin and insulin therapy may increase cancer progression: from our point of view, insulin is a strong inducer of tumor cell migration and proliferation and a promoter of oncogenes such as Akt and PLCγ." (PMID 22554284, 2012). "Finally, different types of cancer could be diversely affected by insulin therapy, as suggested by epidemiological studies." (PMID 23209929, 2012). "In contrast to a German study that an excess cancer risk with insulin glargine emerged after adjustment for dose, our risk estimates for overall cancer and individual sites of cancer did not change substantially after adjusting for insulin dosage." (PMID 21738645, 2011). "Insulin may also indirectly promote cancer development via IGF-1." (PMID 21773024, 2011). "Furthermore, there is evidence that metformin may have insulin independent direct effects of cancer cells, acting as a mammalian target of rapamycin (mTOR inhibitor)." (PMID 21084729, 2010).